ID2 (inhibitor of DNA binding 2)
Diseases named in the same sentence as ID2 in open-access papers (continued):
Sharing a sentence is not in itself a finding about the gene and the disease.
melanoma (15 papers, 2009 to 2025). A malignant, usually aggressive tumor composed of atypical, neoplastic melanocytes. "We found that ectopic expression of Id2 in Treg cells resulted in arrested tumor growth in a B16.F10 melanoma model, which was accompanied with loss of Treg cells and concomitant increase in IFN-γ producing cytotoxic T cells." (PMID 30413714, 2018). "A downregulation of the melanoma oncogene microphthalmia-associated transcription factor (Mitf) was observed, and most likely caused by the inhibition of Id2, a gene that regulated HLH transcription factors such as MITF and also reported to promote tumor cell migration and invasion." (PMID 30157785, 2018). "Although the contribution of the PGC1α-ID2 axis in melanoma metastasis has been well studied, the mechanisms underlying the regulation of ID families by PGC1α is poorly understood in lung cancer." (PMID 33917757, 2021). "The inhibitor of DNA binding 2 (ID2) is an essential component during melanoma metastasis promoted by PGC1α suppression." (PMID 33917757, 2021). "In a melanoma model of cancer, temporal overexpression of Id2 in Treg cells suppresses tumor growth in mice." (PMID 30413714, 2018). "Similar to steady-state, cues derived from NLTs are likely to prime Treg cells located in the draining LNs, as indicated by a higher percentage of cells expressing Batf, Lgals1, Id2, and other NLT markers in melanoma." (PMID 30737144, 2019). "In this report, we show that melanoma cells upregulate ID3 expression (and also ID1 and ID2) in response to vemurafenib (or to the combination vemurafenib + trametinib) in vitro and in patients’ tumors." (PMID 29299138, 2017). "We characterized melanoma cells and conducted dimensionality reduction clustering, revealing six distinct cell subgroups: C0 TRPM1+ Melanoma cells, C1 PIR+ Melanoma cells, C2 PHLDA2+ Melanoma cells, C3 ID2+ Melanoma cells, C4 PCLAF+ Melanoma cells, and C5 CD74+ Melanoma cells." (PMID 39781353, 2025). "PGC1α enhances the transcription of inhibitor of DNA binding 2 (ID2), which in turn binds to and inactivates the transcription factor 4 (TCF4), leading to the downregulated expression of metastasis-related genes and thus impeding melanoma metastasis." (PMID 36003368, 2022). "It has been reported that PGC1α suppresses distant metastasis by mediating a transcriptional circuit comprising the inhibitor of DNA binding 2 (ID2) and transcription factor 4 (TCF4, also called ITF-2 or E2-2), independently of metabolic reprogramming in melanoma." (PMID 33917757, 2021).
lung carcinoma (13 papers, 2009 to 2025). "While our data imply a dominant role for ID1 over ID2 and ID3, purely based on the 5–10‐fold higher expression of ID1 in primary, liver, and lung cancer samples, a modest increase in ID2 and ID3 was also observed between the primary tumour and lung metastases." (PMID 40116596, 2025). "Our results are in direct agreement with a recent report that ID2 exerts its tumor suppressor properties in lung cancer through its effects on cancer cell invasion and migration." (PMID 37487081, 2023). "In that study, besides RNA-Seq analysis, ID2 knockdown promoted lung cancer aggressiveness and led to increase of the cells’ ability to metastasize in vivo." (PMID 37487081, 2023). "Recently, it was reported that ID2 exerts tumor suppressor properties in lung cancer through its effects on cancer cell invasion and migration." (PMID 37487081, 2023). "Given the complexity of the role of ID2 in lung cancer, it is necessary to conduct in-depth research on its detailed mechanisms." (PMID 37497010, 2023). "This proposed mechanism of function of Id2 in lung cancer needs to be validated experimentally in further studies." (PMID 35982951, 2022). "Even though evidence indicates that Id2 exhibits different functions in various cancer types, its function in lung cancer requires further investigation." (PMID 35982951, 2022). "Protein expression levels of Id2 were also higher in the CL1-0 cells than in the other lung cancer cells." (PMID 35982951, 2022). "We reduced gene overexpression’s artificial effect on cell physiology and behavior by establishing an Id2-silenced cell line model; we executed this process because of the frequent inactivation of the tumor suppressor genes in lung cancer." (PMID 35982951, 2022). "We show that the basal BMP activity in lung cancer cell lines is an essential regulator of Id1, Id2, and Id3 expression." (PMID 23593444, 2013). "To date, there is only a single study evaluating the role of ID2 in lung cancer, specifically in small cell lung cancer (SCLC)." (PMID 19129913, 2009). "Altogether, our data suggest that both ID2 expression and intracellular localization must be evaluated in order to determine the prognosis for cancer patients, including those with lung cancer." (PMID 19129913, 2009). "Interestingly, TCGA analysis revealed that high ID2 expression correlates with favorable prognosis in human lung cancer patients which is opposite to GRP78." (PMID 37487081, 2023). "Downregulated ID2 in lung cells dissociates endogenous transcription factor E2A, a positive regulator of the cyclin-dependent kinase inhibitor p21, and finally induces G1/S arrest in lung cancer cells." (PMID 37497010, 2023). "Whether the different subcellular localizations of ID2 could affect its function in lung cancer cells needs to be investigated in the further studies." (PMID 35982951, 2022). "Therefore, the present results suggested that low mRNA expression level of ID1 or high mRNA expression levels of ID2/3/4 predicted an improved survival in patients with lung cancer." (PMID 32003423, 2020). "Therefore, patients with lung cancer with a low mRNA expression level of ID1 or high mRNA expression levels of ID2/3/4 were predicted to have longer OS, FP and PPS." (PMID 32003423, 2020). "In addition, FOXA1 knockdown decreased ID1 and ID2 mRNA and protein levels in lung cancer cells." (PMID 35897813, 2022). "In addition, Id2 overexpression could inhibit lung cancer cells’ proliferation and colony formation." (PMID 35982951, 2022). "Whether Id2 can affect the mesenchymal‐to‐epithelial transition (MET)/epithelial‐to‐mesenchymal transition (EMT) processes in lung cancer cells through Twist regulation requires further investigation; however, our data at least demonstrate that Id2 knockdown increased the mRNA expression of Twist." (PMID 35982951, 2022).
lung carcinoma (continued). "In human lung cancer, nuclear localization of GRP78 leads to the sequestration of inhibitor of DNA binding 2 (ID2), a transcriptional factor that regulates EGFR protein expression." (PMID 40214463, 2025). "Four lung cancer cell lines, A549, H460, H1650, and H1395, were used to explore the relationship between SMURF2 and ID2 expression." (PMID 37497010, 2023). "To further demonstrate the possible regulatory mechanisms of SMURF2 on ID2, we used MG132 and CHX to inhibit degradation and block synthesis in lung cancer cells." (PMID 37497010, 2023). "Notably, the biological function of ID2 in lung cancer remains unclear." (PMID 37497010, 2023). "Because FOXA1 and PGC1α were found to regulate ID1, ID2, and ID3 in lung cancer cells, we investigated the mechanistic impact of ID1 on the loss of FOXA1-mediated EMT in lung cancer cells." (PMID 35897813, 2022). "Ectopic expression of FOXA1 increased ID1, ID2, and ID3 mRNA in A549, H358, and Calu-1 lung cancer cells." (PMID 35897813, 2022). "Our results showed a higher and more dominant expression of ID1 than those of ID2, ID3, and ID4, particularly in lung cancer cell lines." (PMID 33917757, 2021). "In conclusion, our study reveals a potential molecular mechanism of human lung cancer metastasis, mediated by upregulation of GRP78 and its translocation to the nucleus, leading to sequestration of ID2 and activation of genes and pathways impacting migration and invasion." (PMID 37487081, 2023). "Increased ID2 protein levels in lung cancer cells did not further alter CDKN1A transcriptional activity." (PMID 37497010, 2023). "PGC1α was found to promote both ID1, ID2, and ID3 expression in lung cancer cells, suggesting that PGC1α-mediated expression of ID families might be dependent on the transcription factor that is activated by PGC1α." (PMID 35897813, 2022). "We found that PGC1α not only promotes ID1, but also ID2 and ID3 expression in lung cancer cells, suggesting that PGC1α-mediated expression of ID families might be dependent on the cellular context and transcription factors, which are activated by PGC1α." (PMID 33917757, 2021). "Furthermore, ID2-inhibition of endogenous EGFR protein level can be reversed by F-78(WT) but not F-78(NLS Mut) in H1975 human lung cancer cells and HEK293AD cells." (PMID 37487081, 2023). "However, ID2 and ID4 mRNA expression levels were associated with improved OS in patients with lung cancer without a smoking history." (PMID 32003423, 2020).
colon cancer (9 papers, 2010 to 2023). "In contrast, 3/4 colon cancer cell lines exhibited ID2 or ID3 expression loss concomitantly with Dies1 downregulation." (PMID 27721458, 2016). "Recently, it has been reported that retinoic acid receptor-related orphan receptor α (ROR α), Achaete scute-like 2 (ASCL2) and DNA inhibitor binding/differentiation 2 (Id2) bind the promoter region of SEMA3F in colon cancer." (PMID 36119535, 2022). "In colon cancers, which are mostly caused by mutations in the APC (adenomatous polyposis coli) gene and/or β-catenin genes, overexpression of Id2 has been observed and attributed to Id2-promoter activation by up-regulated β-catenin." (PMID 28122577, 2017). "It has been reported that ID2 is a downstream target gene of Wnt signaling in human colon cancer cell lines." (PMID 26163528, 2015). "On the other hand, overexpression of Id2 increases anchorage-independent survival of colon cancer cells." (PMID 26163528, 2015). "Since knockdown of Id2 was reported to suppress the proliferation of colon cancer cells, we next determined polyp size distribution in these mice." (PMID 26163528, 2015). "Overexpression of Id2 increases anchorage-independent proliferation of both SW480 and HT29 colon cancer cells, and knockdown of Id2 decreases cell proliferation of HCT116 cells." (PMID 26163528, 2015). "c-Myc, Snai1, and Id1, but not Tcf4 and Id2, were found to be highly expressed in the colon cancer cell-derived CM-treated group compared to the control (Ctrl) group." (PMID 37996458, 2023). "In addition, the encyclopedia of DNA elements (ENCODE) data also showed that TCF4 binds to a region of the human ID2 promoter that is homologous to the mouse Id2 enhancer in HCT116, a Wnt-signaling activated colon cancer cell line." (PMID 26163528, 2015).
leukemia (9 papers, 2015 to 2022). A malignant (clonal) hematologic disorder, involving hematopoietic stem cells and characterized by the presence of primitive or atypical myeloid or lymphoid cells in the bone marrow and the blood. "Accordingly, further functional studies are needed to determine the underlying molecular mechanism of ID2 in regulating chemosensitivity to cytarabine, daunorubicin, etc. in leukemia cells." (PMID 29190891, 2017). "In addition, loss of Id2 expression is associated with increased MLL-AF9-induced leukemia in mice, and over expression of Id2 inhibits the growth of MV4-11 and MOLM-13 AML cell lines that express MLL-AF9, and Kasumi AML cells that express AML-ETO." (PMID 35990659, 2022). "In addition, loss of Id2 expression is associated with increased MLL-AF9–induced leukemia." (PMID 35775482, 2022). "ID2 expression has been previously shown to be downregulated in translocations of the mixed lineage leukemia gene subtype of AML." (PMID 35490198, 2022). "For example, lncRNA H19 expression was significantly upregulated in bone marrow samples from leukemia patients, which regulated ID2 expression by competitive binding to hsa-miR-19a/b." (PMID 30925672, 2019). "ID2/ID3 protein levels in primary leukemia cells and in MEC1 cells were manipulated by transduction with siRNA reagents." (PMID 25644253, 2015). "Consistent with microarray data, the overall pattern of ID2/ID3 protein expression in relation to cell death/survival responses of primary leukemia cells was suggestive of a pro-survival function for both ID proteins." (PMID 25644253, 2015). "Consequently, due to all the limitations, further studies are required to confirm our results before ID2 could be a potential molecular target for gene therapy against leukemia." (PMID 29190891, 2017).
liver cancer (9 papers, 2020 to 2024). An epithelial or non-epithelial malignant neoplasm that arises from the liver. "Previously the upregulation of SNORD72 has been reported to distinguish cancer from normal counterparts and to promote liver cancer cell invasiveness via stabilizing ID2 mRNA, whereas SNORD92 has been linked to BC patient outcome." (PMID 36585466, 2022). "The m6A methyltransferase KIAA1429 is significantly upregulated in HCC tissues, promoting the migration and invasion of liver cancer cells by increasing the level of m6A in DNA-binding inhibitor 2 (ID2) mRNA." (PMID 39473440, 2024). "VIRMA regulated the migration and invasion of liver cancer by regulating the m6A modification of ID2." (PMID 33731118, 2021). "VIRMA promoted cell migration and invasion in liver cancer by increasing the m6A modification of ID2 mRNA, which then led to the decrease in ID2 expression." (PMID 33731118, 2021). "Additionally, KIAA1429 is significantly upregulated in liver cancer tissues and inhibits ID2 expression by increasing m6A levels in ID2 mRNA, thereby promoting liver cancer cell migration and invasion." (PMID 39445003, 2024). "In addition, KIAA1429 also inhibits ID2 by up-regulating the m6A modification of ID2 mRNA, thus facilitating the migration and invasion of liver cancer." (PMID 38166832, 2024). "Decreasing ID2 could regulate the secretion of vascular endothelial growth factor to promote liver cancer metastasis." (PMID 33731118, 2021). "KIAA1429 is involved in liver cancer progression and regulates the invasion of HCC by altering the m6A modification of ID2 and GATA3." (PMID 32903675, 2020). "Among those genes, CLDN1, ITGA6 and ID2 have been reported to promote EMT, cell migration and proliferation in liver cancer cells, and the resminostat/sorafenib drug combination reduced the mRNA level of these genes (significantly for CLDN1 p = 0.0008, ITGA6 p = 0.0009)." (PMID 33953226, 2021). "Certain studies show that KIAA1429 contributes to liver cancer progression through N6-methyladenosine-dependent post-transcriptional modification of GATA3 and regulates the migration and the invasion of HCC by altering the m6A modification of ID2 mRNA." (PMID 32903675, 2020).
pancreatic cancer (9 papers, 2008 to 2025). "Overexpression of ID2 in pancreatic cancer cells promotes cancer cell growth, while ID1 is linked to increased tumor angiogenesis in pancreatic cancer." (PMID 38195969, 2024). "Recent research has unveiled that ID2 regulated the growth and stemness of pancreatic cancer through the PI3K/Akt pathway, modulating key stemness factors, Nanog and Sox2." (PMID 38195969, 2024). "It has been demonstrated that clock genes, including PER1 and CRY2, are down-regulated, whereas ID2 is over-expressed in pancreatic cancers." (PMID 30934731, 2019). "In another study, we revealed that the tumor-suppressive role of EYA4 in pancreatic tumor growth relies on repression of the transactivation of ID2 via β-catenin Ser675 phosphorylation." (PMID 29764501, 2018). "Id2 is overexpressed in the cancer cells of the pancreatic tumor mass, contributing to cancer cell growth that can be inhibited by Id2 antisense oligonucleotides." (PMID 28122577, 2017). "For example, Id1 and Id2 are both over-expressed in pancreatic cancer cells, and are both considered prognostic markers of squamous cell carcinoma metastasis in the esophageal region." (PMID 23517130, 2013). "In pancreatic cancer, it has also been proven that METTL3 modulates ID2 by m6A methylation to regulate pancreatic cancer cell stemness." (PMID 40495163, 2025). "ID1, ID2 and ID3 are overexpressed in several human tumour entities, e.g. pancreatic cancer and colorectal adenocarcinomas." (PMID 18513385, 2008). "The role of ID1, ID2 and ID3 are expected to be oncogenic due to their overexpression in pancreatic cancer and colorectal adenocarcinomas, respectively." (PMID 18513385, 2008).
bladder cancer (8 papers, 2013 to 2022). "Although a similar relationship between H19 and Id2 has been indicated previously in bladder cancer cells and acute myelocytic leukemia cells, the underlying mechanistic relationship between them have not been well investigated." (PMID 31170091, 2019). "A previous study showed that H19 was positively associated with ID2 expression in bladder cancer." (PMID 29643943, 2018). "H19 has been shown to enhance bladder cancer cell proliferation via the upregulation of an inhibitor of DNA binding 2 (ID2)." (PMID 36685879, 2022). "ID2 has been shown overexpressed in several cancer tissues or cells, such as salivary gland cancer and bladder cancer, and promote cancer invasion, proliferation, and metastasis." (PMID 34873426, 2021). "Recent data on bladder cancer documented how upregulated H19 increased cancer cell proliferation by increasing inhibitor of DNA binding 2 (ID2) expression." (PMID 23860209, 2013). "Over-expression of H19 resulted in a significant increase in expression of ID2 (inhibitor of DNA binding/differentiation 2), whereas a knockdown of H19 expression decreased ID2 expression, suggesting that up-regulated H19 increases bladder cancer growth by regulating ID2 expression." (PMID 24006935, 2013). "The ID2 upregulation attenuates retinoblastoma protein (Rb) effects on E2F1 expression, thereby promoting bladder cancer progression." (PMID 36685879, 2022).
acute myeloid leukemia (7 papers, 2010 to 2022). Acute myeloid leukemia (AML) is a group of neoplasms arising from precursor cells committed to the myeloid cell-line differentiation. "ID2 is known to be associated with chemotherapy response and prognosis in acute myeloid leukemia." (PMID 31874600, 2019). "Concomitantly elevated expression levels of HOXA9 and HOXA10 together with ID2 in cell lines containing MLL translocations confirmed this form of regulation in both ALL and acute myeloid leukemia." (PMID 20565746, 2010). "On the other hand, we observed that patients showing higher expression of ID2 have better survival in CCA, which was also observed in acute myeloid leukemia (AML)." (PMID 33193605, 2020).
Ewing sarcoma (7 papers, 2009 to 2023). A small round cell tumor that lacks morphologic, immunohistochemical, and electron microscopic evidence of neuroectodermal differentiation. "Ewing sarcoma, which is manifested with fever and visual disturbance, has been reported to be correlated with up-regulation of ID2, and in fact, vision deficiency is common in MPS." (PMID 32050523, 2020). "Many of the top ranked super-enhancer associated genes were genes of known relevance in Ewing sarcoma, including caveolin 1 (CAV1), NKX2.2, ID2 and CCND1." (PMID 26337082, 2015). "Here, we demonstrated that ZSTK474 partially downregulated transcriptional activity of the EWSR1-FLI1 transcription factor from the Id2 promoter via a reporter assay, and suppressed expression of the Id2 protein in both of the Ewing's sarcoma cell lines examined." (PMID 30416685, 2018). "Instead, we found that ZSTK474 reduced the expression level of Id2, which was transcriptionally regulated by EWSR1-FLI1, in the Ewing's sarcoma cell lines." (PMID 30416685, 2018). "Induction of differentiation in tumor cells could be triggered by down regulation of Notch-1 and ID2, both of which were indeed down regulated very clearly due to combination of EWS shRNA plasmid transfection and TFL treatment in Ewing’s sarcoma SK-N-MC and RD-ES xenografts." (PMID 27547487, 2014).